ENSG00000293615 (novel protein, AC136007.2-ASPRV1 readthrough)
Synonyms: ADLI; MUNO; SASP; SASPase; Taps; ASPRV1
Gene: Protein-coding gene on chromosome 2 (69,960,104 to 70,087,320, reverse strand). Ensembl gene ENSG00000293615.
Diseases named in the same sentence as ENSG00000293615 in open-access papers:
ENSG00000293615 is named in the same sentence as 2 diseases in open-access papers, as found by Europe PMC text mining. Sharing a sentence is not in itself a finding about the gene and the disease.
ENSG00000293615 shares sentences with these, for which no sentence is quoted: breast carcinoma (1 paper); hypothyroidism (1).